RAB31 (RAB31, member RAS oncogene family)
Description:
The small GTPases Rab are key regulators of intracellular membrane trafficking, from the formation of transport vesicles to their fusion with membranes. Rabs cycle between an inactive GDP-bound form and an active GTP-bound form that is able to recruit to membranes different set of downstream effectors directly responsible for vesicle formation, movement, tethering and fusion. Required for the integrity and for normal function of the Golgi apparatus and the trans-Golgi network. Plays a role in insulin-stimulated translocation of GLUT4 to the cell membrane. Plays a role in M6PR transport from the trans-Golgi network to endosomes. Plays a role in the internalization of EGFR from the cell membrane into endosomes. Plays a role in the maturation of phagosomes that engulf pathogens, such as S.aureus and M.tuberculosis.
Synonyms: RAB22B
Tractability: Small molecule: a structure with a bound ligand is known. Antibody: its Gene Ontology location is reachable by antibodies, with high confidence. PROTAC: ubiquitination databases record sites on it; its protein half-life has been measured.
Gene: Protein-coding gene on chromosome 18 (9,708,246 to 9,862,551, forward strand). Ensembl gene ENSG00000168461.
Subcellular location: Golgi apparatus, trans-Golgi network; Golgi apparatus, trans-Golgi network membrane; Early endosome; Cytoplasmic vesicle, phagosome; Cytoplasmic vesicle, phagosome membrane
Subcellular location (Human Protein Atlas): Golgi apparatus; Vesicles
Pathways (Reactome):
Immune System: Neutrophil degranulation
Metabolism of proteins: RAB geranylgeranylation
Vesicle-mediated transport: RAB GEFs exchange GTP for GDP on RABs
Gene Ontology:
Molecular function: G protein activity; GDP binding; GTP binding; GTPase activity; protein binding
Biological process: cellular response to insulin stimulus; Golgi to plasma membrane protein transport; phagosome maturation; receptor internalization; regulated exocytosis; endocytosis; positive regulation of phagocytosis, engulfment; Golgi vesicle transport
Cellular component: early endosome; Golgi apparatus; phagocytic vesicle; trans-Golgi network membrane; cytosol; early endosome membrane; early phagosome membrane; phagocytic cup; plasma membrane; secretory granule membrane; cytoplasm; late endosome; phagocytic vesicle membrane; trans-Golgi network
Genetic constraint (gnomAD): Loss-of-function variants: 17 observed, 16.78 expected, observed/expected ratio (o/e) 1.01, 90% interval 0.69 to 1.52. The upper end of that interval is the gene's LOEUF score, 1.52, which puts it in group 6 of 6, group 1 being the genes least tolerant of losing a copy. Missense variants: 167 observed, 184.4 expected, observed/expected ratio (o/e) 0.91, 90% interval 0.8 to 1.03. Synonymous variants: 70 observed, 63.41 expected, observed/expected ratio (o/e) 1.1, 90% interval 0.91 to 1.35.
Homologues: Orthologues: chimpanzee RAB31 (100% identical), macaque RAB31 (98% identical), mouse Rab31 (94% identical), pig RAB31 (94% identical), rat Rab31 (94% identical), guinea pig RAB31 (94% identical), dog RAB31 (93% identical), tropical clawed frog rab31 (88% identical). Paralogues in human: RAB22A (71% identical), RAB5C (45% identical), RAB5A (45% identical), RAB10 (42% identical), RAB5B (42% identical), RAB2B (41% identical), RAB21 (41% identical), RAB7A (40% identical), RAB17 (39% identical), RAB30 (39% identical), RAB11B (38% identical), RAB2A (38% identical), and 56 more.
Diseases named in the same sentence as RAB31 in open-access papers:
RAB31 is named in the same sentence as 41 diseases in open-access papers, as found by Europe PMC text mining. Sharing a sentence is not in itself a finding about the gene and the disease. The quoted sentences say what the papers report.
breast carcinoma (19 papers, 2012 to 2025). "Rab31 is also a member of the Rab5 family proteins, and has been reported to be associated with the malignant behavior of breast cancer, ovarian cancer, and glioblastoma." (PMID 36329997, 2022). "High expression of Rab31 is frequently observed in breast cancer tissues 16 and is associated with enhanced cell proliferation." (PMID 34975321, 2022). "Increased Rab31 protein levels were associated with enhanced proliferation of breast cancer cells, reduced cell adhesion and decreased invasive capacity in vitro and in vivo." (PMID 34906074, 2021). "Increased RAB31 expression is significantly associated with distant metastasis-free survival and overall survival rate in breast cancer." (PMID 33072555, 2020). "RAB31 has been reported to be associated with the malignant behavior of breast cancer, hepatocellular carcinoma, and gastric cancer." (PMID 33072555, 2020). "Established as a breast cancer marker with good prognostic value, the overexpression of Rab31 is associated with estrogen receptor positive (ER+) breast cancer." (PMID 31973201, 2020). "High Rab31 level in tumor tissues was associated with worse 5-year DFS in patients with breast cancer." (PMID 30064475, 2018). "Well recognized as a breast cancer marker with good prognostic value, recent findings have provided some insights as to the mechanism underlying Rab31's influence on oncogenesis." (PMID 25472813, 2015). "Rab31, a member of the Rab5 subfamily, has recently emerged as a membrane traffic modulator that has interesting associations with breast carcinoma as well as glioma, and is the focus of this review." (PMID 25472813, 2015). "In concert with such a model, chloroquine treatment of breast cancer cells silenced for Rab31 was associated with increases in MUC1-C abundance, indicating that Rab31 promotes recycling of MUC1-C, as opposed to its lysosomal degradation." (PMID 22792175, 2012). "The present studies demonstrate that silencing of MUC1-C in ER+ breast cancer cells is associated with downregulation of transcripts encoding the Rab31 GTPase." (PMID 22792175, 2012). "Quantification of mRNA levels of uPAR-del4/5 in tumor tissues revealed that higher uPAR-del4/5 expression - similar to rab31 - is associated with shorter disease-free survival of breast cancer patients." (PMID 22920728, 2012). "Increased rab31 protein levels were associated with enhanced proliferation of breast cancer cells, led to a reduced adhesion of cells towards extracellular matrix proteins and decreased invasive capacity through MatrigelTM." (PMID 22920728, 2012). "Rab31 expression in breast cancers is also significantly associated with decreases in overall survival." (PMID 22792175, 2012). "Gene microarray analysis of MCF-7 breast cancer cells demonstrated that silencing of MUC1 is associated with decreases in Rab31 expression." (PMID 22792175, 2012). "Rab31 is a member of the Ras superfamily of small GTPases that has been linked to poor outcomes in patients with breast cancer." (PMID 22792175, 2012). "Of note, high expression of RAB31 is associated with a worse outcome in patients with breast cancer." (PMID 22724020, 2012). "However, the precise mechanisms underlying the role of Rab31 in breast cancer remain to be elucidated." (PMID 41463174, 2025). "Specifically, the knockdown of Rab31 expression in Cx43-overexpressing cells significantly suppressed the expression of autophagy-related proteins and attenuated the phenotypic characteristics associated with breast cancer." (PMID 41463174, 2025). "Rab31 transcripts were also found to be elevated in breast cancer cells expressing the urokinase-type tissue plasminogen activator (uPA)-receptor splice variant uPAR-del4/5, and high Rab31 levels were significantly associated with distant metastasis-free survival and overall survival." (PMID 25472813, 2015).
breast carcinoma (continued). "A new key finding in this regard is that the Rab31 promoter region has an ER responsive element, and could be thus regulated or deregulated in breast cancer cells by trans factors associating with the element." (PMID 25472813, 2015). "Elevated rab31 protein levels were associated with enhanced proliferation of breast cancer cells." (PMID 22920728, 2012). "On one hand, overexpression of rab31 caused enhanced cell growth of breast cancer cells." (PMID 22920728, 2012). "A splice variant of uPAR, uPAR-del4/5, which is unable to bind uPA, is a known prognostic marker for breast cancer although phenotypically, in vitro, cells overexpressing this variant appear to have reduced invasive properties, much like that observed for Rab31." (PMID 25472813, 2015). "This indicates that inhibiting Rab31 expression effectively reverses the effects of Cx43 overexpression, which otherwise activates autophagy and promotes breast cancer cell proliferation, migration, and invasion." (PMID 41463174, 2025). "To further investigate the impact of Rab31 on the biological characteristics of breast cancer cells, we conducted a series of experiments involving Rab31 knockdown and overexpression." (PMID 41463174, 2025). "To further investigate the role of Cx43 binding to Rab31 in autophagy and breast cancer cell biology, we knocked down Rab31 expression in MDA-MB-231 cells overexpressing Cx43." (PMID 41463174, 2025). "Different from the results obtained in breast cancer cells, we found that Rab31 expression is enhanced with cisplatin treatment and Rab31 increased cisplatin resistance in STAD cells." (PMID 36781842, 2023). "Increased expression of Rab31 is related to enhanced proliferation, leading to a decreased invasive capacity of breast cancer cells." (PMID 36781842, 2023). "Rab31 is highly expressed in breast cancer 16, gastric cancer 21, pancreatic cancer 19 and other malignancies." (PMID 34975321, 2022). "In the present study, we extended the analyses of the Rab31 effects on breast cancer cell proliferation using a 3D cell culture model." (PMID 34906074, 2021). "Here, we used a profiler PCR array system to assess the regulation of genes involved in EMT/MET in Rab31 overexpressing CAMA-1 breast cancer cells versus the respective vector transfectants displaying only low endogenous Rab31 levels." (PMID 34906074, 2021). "Subsequently, protein expression of Rab31 and mucin-1 was analyzed in tumor tissue extracts of ER + breast cancer and was found to be correlated with patients’ prognosis." (PMID 34906074, 2021). "We previously showed that Rab31 overexpression attenuates invasion and enhances proliferation of breast cancer cells through inhibition of the EMT-like phenotype and the switch to the more proliferative MET-like phenotype." (PMID 34906074, 2021). "Using breast cancer cell transfectants displaying different Rab31 mRNA expression levels, the modulatory role of Rab31 in tumor biologically-relevant processes was investigated." (PMID 34906074, 2021). "We identified TGFB1 as the most strongly regulated gene in ER + CAMA-1 breast cancer cells (> 25-fold down-regulation in Rab31 overexpressing cells)." (PMID 34906074, 2021). "It is postulated that the overexpression of Rab31 in ER+ breast cancer is due to the ER responsive element in the Rab31 promoter region that results in an estrogen-induced activation of gene transcription." (PMID 31973201, 2020). "Breast cancer cell lines with RAB31 overexpression in vitro switch from an invasive to a more proliferative phenotype, suggesting a pro-tumorigenic role for this protein in the respective cancer types." (PMID 33072555, 2020). "Rab31 was found to play critical role in tumor development and is an independent prognostic factor in breast cancer." (PMID 32695142, 2020). "Beyond breast cancer, Rab31 regulates the PI3K/AKT axis in hepatocellular carcinoma (HCC) cells, with KD of Rab31 increasing caspase 3 and 7 activity in human MHCC97 HCC cells." (PMID 31973201, 2020).
breast carcinoma (continued). "Numerous studies have reported that Rab31 participates in tumor initiation and progression across various cancers, including breast cancer, glioblastoma, and pancreatic cancer." (PMID 32695142, 2020). "Rab31 levels are elevated in breast cancer cells, and recent findings offer two explanations for the phenomenon." (PMID 25472813, 2015). "When breast cancer cells moderately overexpressing Rab31 were xenografted onto nude mice, these exhibited significantly reduced lung metastasis compared to control cells." (PMID 25472813, 2015). "Another possibility is related to the observation that Rab31 is selectively elevated in ERα-positive breast cancer samples." (PMID 25472813, 2015). "A Serial Analysis of Gene Expression (SAGE) profiling found Rab31 to be among 11 genes that are robustly overexpressed in samples of Oestrogen Receptor α (ERα) positive breast carcinomas." (PMID 25472813, 2015). "Other than breast cancer, Rab31 is also identified as one of the cohort (race)-dependent associations with glioblastoma survival." (PMID 25472813, 2015). "MUC1-C and Rab31 therefore appear to form an auto-inductive loop that results in sustained over-expression of MUC1-C in breast cancer cells." (PMID 25472813, 2015). "In order to analyze the effect of rab31 overexpression on tumor cell adhesion, rab31-transfected breast cancer cells were incubated on polystyrene plates coated with different extracellular matrix (ECM) proteins." (PMID 22920728, 2012). "Rab31 was identified as one out of 11 genes that are overexpressed in estrogen receptor (ER)-positive breast cancer patients." (PMID 22920728, 2012). "To analyze possible cellular effects of variable rab31 protein expression, we stably transfected breast cancer cell lines with the eukaryotic expression plasmid pRcRSV harboring the rab31 cDNA sequence." (PMID 22920728, 2012). "Several Rab proteins, including rab31, have been shown to affect cancer progression and are related with prognosis in various types of cancer including breast cancer." (PMID 22920728, 2012). "Overexpression of rab31 in breast cancer cells leads to a switch from an invasive to a proliferative phenotype as indicated by an increased cell proliferation, reduced adhesion and invasion in vitro, and a reduced capacity to form lung metastases in vivo." (PMID 22920728, 2012). "The present results demonstrate that MUC1-C induces Rab31 expression in estrogen receptor positive (ER+) breast cancer cells." (PMID 22792175, 2012). "In fact, when HuR expression was silenced in epithelial 184B5Me breast cancer cells, a significant reduction of rab31 mRNA expression was observed." (PMID 22920728, 2012). "First, various breast cancer cell lines were analyzed by quantitative PCR for endogenous rab31 mRNA expression levels." (PMID 22920728, 2012). "By contrast, increased expression of rab31 in breast cancer cells led to reduced adhesion towards several extracellular matrix proteins and decreased invasive capacity through MatrigelTM." (PMID 22920728, 2012). "In turn, Rab31 contributes to the upregulation of MUC1-C abundance in breast cancer cells by attenuating degradation of MUC1-C in lysosomes." (PMID 22792175, 2012). "Because the generated polyclonal antibodies turned out to be highly specific for rab31, rab31 protein expression was verified in breast cancer tissue by immunohistochemistry." (PMID 22920728, 2012). "On the other hand, high levels of rab31 in breast cancer cells resulted in significantly reduced adhesion towards ECM proteins as well as decreased invasive capacity." (PMID 22920728, 2012). "Collectively, we hypothesize that Cx43 promotes distant metastasis of breast cancer by influencing autophagy via Rab31, potentially offering novel insights and therapeutic targets for clinical breast cancer research and treatment." (PMID 41463174, 2025).
breast carcinoma (continued). "Notably, Rab31 regulates the switch between an invasive and proliferative phenotype in breast cancer cells, which depends on its expression level." (PMID 36781842, 2023). "Studies have shown the expression levels of RAB31 may serve as a crucial regulator of the transition between invasiveness and proliferation of breast cancer cells." (PMID 37207166, 2023). "This prompted us to analyze whether Rab31 overexpression in breast cancer cells affects expression of genes involved in epithelial-to-mesenchymal transition (EMT)-like processes when compared to Rab31 low-expressing cells." (PMID 34906074, 2021). "In breast cancer tissue, Rab31 was reported to be strongly up-regulated." (PMID 34906074, 2021). "Overexpression of Rab31 in breast cancer cells, resulting in downregulation of TGF-ß, may lead to a deregulation of the balance between cell cycle arrest and cell proliferation in favor of tumor growth." (PMID 34906074, 2021). "It is reasonable to assume that some of the genes previously linked to EMT-like processes may also play a role in the effects mediated by Rab31 in breast cancer cells." (PMID 34906074, 2021). "Indeed, overexpression of Rab31 promotes the shift from an invasive to proliferative phenotype in breast cancer cells and in xenograft mouse models." (PMID 31973201, 2020). "Interestingly, RAB31 gene is member of the Ras superfamily, which can promote cell proliferation and migration in breast cancer cells." (PMID 28178669, 2017). "Given that Rab31 overexpression in breast cancer cell lines increased their proliferation, the discrepancy may be down to cell type differences." (PMID 25472813, 2015). "Given that overexpression of Rab31 in breast cancer cell lines actually enhanced proliferation, Rab31, when elevated in the presence of MUC1-C may enhance instead of retard EGFR signalling in these cells." (PMID 25472813, 2015). "On the face of it, our observations in A431 cells run counter to what might be expected for Rab31 overexpression in breast cancer cells." (PMID 25472813, 2015). "Interestingly, when Rab31 is overexpressed in breast cancer cell lines, it enhanced proliferation and diminished cell adhesion towards several extracellular matrix (ECM) components, as well as attenuated cell invasion through Matrigel." (PMID 25472813, 2015). "In order to explore the impact of rab31 overexpression in breast cancer cells on the capacity of these cells to form lung metastases in vivo, batch-transfected MDA-MB-231 cells tagged with the lacZ-gene were injected into the tail veins of immune-compromised female nude CD1 nu/nu mice." (PMID 22920728, 2012). "Finally, in a xenograft mouse model, we observed a significantly impaired metastatic dissemination of rab31 overexpressing MDA-MB-231 breast cancer cells to the lung." (PMID 22920728, 2012). "Therefore, in the present study we aimed at analyzing the impact of differential rab31 expression in breast cancer cells on important aspects of tumor progression in vitro and in vivo." (PMID 22920728, 2012). "In addition and in concert with our finding that ERα activates Rab31 gene transcription, Rab31 expression was also significantly higher in ER+ as compared to ER- breast cancers." (PMID 22792175, 2012). "The present studies demonstrate that MUC1-C induces Rab31 expression in breast cancer cells." (PMID 22792175, 2012). "However, no insights are available regarding a potential functional role for Rab31 in breast cancer." (PMID 22792175, 2012). "Rab31 expression levels were also significantly higher in ER+ breast cancers (right)." (PMID 22792175, 2012). "Finally, our study has identified that Cx43 is highly expressed in triple-negative breast cancer cells and may activate autophagy-related pathways through the regulation of Rab31, thereby influencing the progression of breast cancer." (PMID 41463174, 2025).